CRP (C-reactive protein)
Diseases named in the same sentence as CRP in open-access papers (continued):
Sharing a sentence is not in itself a finding about the gene and the disease.
necrotizing fasciitis (36 papers, 2014 to 2026). "The Laboratory Risk Indicator for Necrotizing Fasciitis score, with a cut-off value of 6 and C-reactive protein (CRP) + the neutrophil-to-lymphocyte ratio (NLR), with a cut-off of 27, were remarkably useful for the exclusion diagnosis for Group IV." (PMID 36503406, 2022). "Some of the scoring systems like the retrospective risk score called LRINEC (Laboratory Risk Indicator for Necrotizing Fasciitis) was calculated by summating values of CRP, total count, hemoglobin, sodium, creatinine and glucose that are complimentary to diagnosis." (PMID 33833953, 2021). "The LRINEC (laboratory risk indicator for necrotizing fasciitis) score is used clinically, consisting of a 13-point scoring system based on the results of routine laboratory tests (C-reactive protein, total white cell count, hemoglobin, sodium, creatinine, and glucose)." (PMID 34145466, 2021). "A widely used tool to aid in the diagnosis of necrotizing fasciitis is the Laboratory Risk Indicator for Necrotizing Fasciitis (LRINEC), which incorporates C-reactive protein levels, white blood cell count, hemoglobin, sodium, creatinine, and glucose levels." (PMID 41510471, 2025). "The LRINEC score, designed to distinguish necrotizing fasciitis from other soft tissue cellulitis, requires C‐reactive protein(CRP), white blood cells, hemoglobin, sodium, glucose, and creatinine for calculation." (PMID 37565057, 2023). "This study suggests that using non-invasive tests, such as PCT, the LRINEC scoring system, and other markers (CRP, creatine kinase, "pain out of proportion," creatinine, and lactate), can detect necrotizing fasciitis early in its course." (PMID 30094111, 2018). "While there is an emphasis on PCT and the LRINEC scoring system, increased levels of C-Reactive Proteins (CRP) and “pain out of proportion” can also be contributing factors to the clinical score in necrotizing fasciitis." (PMID 30094111, 2018). "These co-morbid factors and CRP (levels greater than 150 mg/liters), low Hb, low erythrocytes, and severe pain can all serve as major factors in determining the diagnosis of necrotizing fasciitis." (PMID 30094111, 2018). "In addition to the LRINEC score, the NEJM algorithm was used to detect necrotizing fasciitis in patients with tachycardia (heart rate >120 bpm), hypotension, an elevated creatine kinase level, and a C‐reactive protein (CRP) level of >15 mg/dL." (PMID 39916636, 2025). "There was an increasing pattern in all inflammatory and hematologic factors, including WBC, neutrophil, CRP, NLR, CRP + NLR, platelet-to-lymphocyte ratio (PLR), systemic immune-inflammation index (SII), and the Laboratory Risk Indicator for Necrotizing Fasciitis (LRINEC)." (PMID 38539204, 2024). "Several scoring systems have been developed as a diagnostic aide, such as the laboratory risk indicator for necrotizing fasciitis (LRINEC) score based on the following laboratory parameters: white blood cell count, hemoglobin, glucose, creatinine, sodium, and c-reactive protein." (PMID 37109703, 2023). "A study suggested that there is a five-fold increase in CRP in necrotizing fasciitis." (PMID 30094111, 2018). "As the C-reactive protein (CRP) level was not tested at that time, the laboratory risk indicator for necrotizing fasciitis (LRINEC) score was assumed to be around 5, indicative of potential NF." (PMID 29642157, 2018). "In the present study, microbiological cultures collected during the fasciitis episodes remained negative; CRP levels were high and neutrophil counts exceptionally so, without clinically evident responses to antibiotics." (PMID 36892687, 2023). "But, neither CRP nor creatine kinase had a prognostic value among the necrotizing fasciitis group and can only be isolated markers for diagnosis." (PMID 30094111, 2018).
necrotizing fasciitis (continued). "Despite the patient’s well-being and normal CRP, the choice of performing surgical exploration was not instinctive but made mainly because of the significant CK elevation and the radiologist’s report raising a high suspicion index of necrotizing fasciitis." (PMID 32811562, 2020). "Although increased levels of CRP (>15.5 mg/dl) and age > 35 years are described to be predictors of retropharyngeal abscesses and necrotizing fasciitis, it is proven, and our data confirm, that neither CRP nor leukocytes in sera are appropriate markers to distinguish between PTA and AT." (PMID 29180834, 2017).
sarcoidosis (36 papers, 2012 to 2025). Sarcoidosis is a multisystemic disorder of unknown cause characterized by the formation of immune granulomas in involved organs. "Among sarcoidosis patients, the mean capillary absolute number negatively correlated with the C-reactive protein concentrations and was positively associated with the forced vital capacity percentage." (PMID 36040491, 2022). "CRP is a systemic inflammation marker associated with sarcoidosis progression and may help identify patients at higher risk for activation." (PMID 39852350, 2024). "Moreover, elevated CRP appears to identify a subset of cases with more severe disease, but a study proposed hsCRP as a useful marker to discard sarcoidosis, and another study found that children with pediatric sarcoidosis were associated with elevated CRP values." (PMID 37873776, 2023). "Currently, blood biomarkers such as ACE, sIL-2R, CD163, CCL18, serum amyloid A, and CRP are employed to aid in the diagnosis and monitoring of sarcoidosis." (PMID 39852350, 2024). "The mean CRP level in the sarcoidosis group and the TB group was 24 mg/dL and 39 mg/dL, respectively (p = 0.003)." (PMID 38787250, 2024). "We evaluated if sarcoidosis cytokine profiles, CRP, and IgG are different in two MIF classification groups." (PMID 36207373, 2022). "Despite clinical remission, sarcoidosis was characterized by significantly higher concentrations of inflammatory markers, such as CRP, IL-6, and fibrinogen." (PMID 36494464, 2022). "When analyzing the correlations per diagnostic group, only in sarcoidosis and IPF patients the correlation between SAA and CRP remained significant (R = 0.384 and R = 0.598, respectively, both p < 0.001)." (PMID 33799927, 2021). "CRP values below a cut-off of cut-off 0.15 mg/dl showed 73.3% sensitivity and 66.7% specificity in discriminating sarcoidosis patients from those of other groups." (PMID 33089426, 2020). "Sarcoidosis patients showed the best areas under the curve (AUC) than patients with other ILDs for KL-6 (AUC = 0.82, 95%CI 0.71–0.92; p < 0.001), CRP (AUC = 0.72, 95%CI 0.57–0.86; p = 0.008) and WBC (AUC = 0.712, 95%CI 0.57–0.85 p = 0.0039)." (PMID 33089426, 2020). "While mean CRP values of our patients with sarcoidosis were 12.16 ± 15.71, the averages of ESR values were detected as 24.57 ± 18.36." (PMID 33062080, 2020). "In the logistic regression, sarcoidosis was tested as dependent variable, while KL-6, CRP and WBC were tested as independent variables." (PMID 33089426, 2020). "IPF and sarcoidosis patients showed differences in CRP (p = 0.01), Hb (p = 0.01), HCT (p = 0.02), WBC (p < 0.001), PLT (p = 0.02), creatinine (p = 0.02) and GPT (p = 0.03) values." (PMID 33089426, 2020). "A diagnosis of sarcoidosis was associated with values of three different parameters: KL6, WBC and CRP, enabling this granulomatous inflammatory disorder to be distinguished from the fibrotic lung diseases IPF and cHP." (PMID 33089426, 2020). "In particular, CRP values resulted decrease in Sarcoidosis patients than HP (p = 0.005) and IPF (p = 0.00007)." (PMID 33089426, 2020). "In support of the sarcoidosis diagnosis elevated C-reactive protein (CRP), erythrocyte sedimentation rate, and angiotensin-converting enzyme (ACE) levels were found." (PMID 31771516, 2019). "High-sensitivity C-reactive protein (hs-CRP) methods have recently been introduced to accurately monitor minor increases in serum CRP but limited studies evaluating hs-CRP in sarcoidosis have been reported." (PMID 30154391, 2018). "We aimed to investigate the diagnostic features of YKL-40, sIL-2R, ACE, hs-CRP, neopterin concentrations and ADA markers in active and inactive discrimination of sarcoidosis disease." (PMID 30154391, 2018). "The CRP response (although rather minor) was present in the majority of patients and appeared indicative of the inflammatory activity of sarcoidosis." (PMID 30154391, 2018).
sarcoidosis (continued). "In inactive sarcoidosis patient group, hs-CRP was moderately correlated with age (r: correlation coefficient) (r = 0.427; p < 0.01) and sIL-2R (r = 0.464, p < 0.01)." (PMID 30154391, 2018). "Previous work showed that ESR and CRP levels are higher in sarcoidosis patients compared to controls." (PMID 27433355, 2016). "In our study changes in the healthy conditions, in the imaging diagnostics of the chest and in levels of three major immunoglobulins (IgG, IgM and IgA) as well as CRP value with respect to sarcoidosis and the age and gender were shown." (PMID 27562460, 2016). "On dichotomizing CRP values, sarcoidosis patients with sHTN had a significantly higher frequency of CRP >2 mg/L (P = 0.003), CRP >2.5 mg/L (P = 0.004), CRP >3 mg/L (P = 0.001), and CRP >3.5 mg/L (P = 0.01)." (PMID 27433355, 2016). "Serum levels of CXCL9, CXCL10, and proteins associated with inflammation and/or disease activity (sIL2R, ACE, ESR and CRP) were measured in a prospective cohort of sarcoidosis subjects and controls." (PMID 24199653, 2013). "Also, ESR and CRP were found to be elevated in sarcoidosis patients; similarly, this was noted in our patient." (PMID 38978890, 2024). "CRP is regarded as the major pro-inflammatory acute phase protein related to sarcoidosis." (PMID 33089426, 2020). "Our results, showing lower concentrations of CRP in sarcoidosis patients than in patients with IPF and CHP, may be useful to exclude other causes of ILD in the diagnostic workup of sarcoidosis." (PMID 33089426, 2020). "We conclude that the level of systemic inflammation in sarcoidosis patients—reflected by a higher ESR, CRP—may be associated with the presence of sHTN." (PMID 27433355, 2016). "The association between CRP and sHTN has been previously demonstrated in other studies not related to sarcoidosis." (PMID 27433355, 2016). "ROC curve analysis for CRP revealed an AUC value of 0.644 (95% CI 0.518–0.769, P = 0.03) and a cutoff value of 3 mg/L yielded a 37% sensitivity and 95% specificity for predicting the presence of sHTN in this cohort of sarcoidosis subjects." (PMID 27433355, 2016). "It was recently shown that active sarcoidosis could be differentiated from the inactive one through an algorithm involving the association of plasma CHIT1 activity, ACE levels, and high-sensitivity C-reactive protein (hs-CRP) levels." (PMID 34830565, 2021). "Additional serum biomarkers for sarcoidosis include neopterin, lysozyme, human cartilage glycoprotein-39 (YKL40), CD163, CCL18, serum amyloid A, and C-reactive protein (CRP)." (PMID 39852350, 2024). "In the logistic regression model, KL-6, CRP and WBC showed areas under curves (AUC) 0.86, for sarcoidosis diagnosis." (PMID 33089426, 2020). "No statistical difference was recorded on the concentrations of CRP and APOA2 among the IPF, sarcoidosis and hypersensitivity pneumonitis groups." (PMID 28122020, 2017). "The serum concentrations of HBB, CRP and SERPINA1 in IPF, sarcoidosis and hypersensitivity pneumonitis patients were higher compared to the healthy control group." (PMID 28122020, 2017). "For example, it is known that sarcoidosis patients with active disease have very high levels of ESR and CRP." (PMID 27433355, 2016). "The concentrations of ACE, CRP, ESR, CXL9, CXCL10, and sIL2R were all significantly elevated in sarcoidosis subjects when compared to control subjects." (PMID 24199653, 2013). "Sarcoidosis patients in the active phase of the disease were significantly higher YKL-40, sIL-2R, hs-CRP levels and ACE activity than those in the inactive phase, while ADA activities and neopterin levels did not display any significant difference between the active and inactive disease groups." (PMID 30154391, 2018). "In addition, CRP showed AUCs of 0.8825, 0.7000 and 0.7100 for discriminating IPF and healthy controls, IPF and sarcoidosis, and IPF and hypersensitivity pneumonitis, respectively." (PMID 28122020, 2017).
sarcoidosis (continued). "We observed that, among sarcoidosis subjects, ESR and CRP levels are almost twice as high in hypertensive subjects compared with normotensive patients (48.8 versus 23.2 mm/hr, P = 0.001 for ESR, and 3.4 versus 1.7, P = 0.067 for CRP)." (PMID 27433355, 2016). "CRP was decreased, but only transiently, and changes in CRP levels did not correlate with clinical efficacy in that sarcoidosis study." (PMID 22300528, 2012). "Serum MIP-1beta and TNF-RII, but not CRP, were previously shown to be significantly decreased by infliximab treatment in sarcoidosis patients, with the decreases in these biomarkers correlating with the extent of clinical efficacy." (PMID 22300528, 2012). "Interestingly CRP, not hsCRP, varied significantly between the non-active and the active sarcoidosis group." (PMID 37510860, 2023). "Although acute phase proteins such as CRP and SAA correlate quite well in several diseases, in our study SAA levels are higher in sarcoidosis patients with a pulmonary fibrotic phenotype compared to sarcoidosis patients without fibrosis, while CRP levels do not differ between these groups." (PMID 33799927, 2021). "However, CD200R expression in sarcoidosis did not correlate with serum C-reactive protein or plasma viscosity, signifying that a CD200Rlow monocyte phenotype is not a manifestation of systemic inflammation." (PMID 27929051, 2016). "Extensive additional investigations were performed because of the persistent elevation of ESR and CRP, which ruled out chronic infections, including TBC and endocarditis, and auto-immune diseases including SLE and sarcoidosis." (PMID 33715142, 2021). "An elevated CRP of 70 (< 10 mg/L) and a normal ACE level of 93 (30–115 U/l) was interpreted as no sign of sarcoidosis reactivation." (PMID 31771516, 2019). "Of note, levels of non-specific markers of inflammation as well as “sarcoidosis-related” serum markers, such as sIL2R, ESR, CRP, and ACE level, did not correlate with pulmonary function measures or severity score." (PMID 24199653, 2013). "COPD patients expressing the highest baseline CRP or TNF-alpha levels also did not demonstrate a significant impact of infliximab on changes from baseline in clinical and biomarker measurements, unlike results recently reported for sarcoidosis." (PMID 22300528, 2012). "Significantly higher concentrations of CRP (but not hsCRP), 3.0 vs. 6.3 mg/L (p = 0.03327); INF-gamma, 9.94 vs. 12.74 pg/mL (p = 0.01606); neopterin, 5.20 vs. 8.82 nmol/L (p = 0.02139); and sIL-2R, 3.52 vs. 9.44 pg/mL (p = 0.0002342) were observed in patients with active sarcoidosis." (PMID 37510860, 2023).
thyroiditis (36 papers, 2005 to 2026). Inflammation of the thyroid gland. "In a large cohort, some authors found that in a subgroup of patients, a CRP gene variant is associated with thyroid disorders and mostly with rapid cycling, especially in women." (PMID 35041295, 2022). "Studies have indicated that patients with pSS with lung involvement may exhibit elevated levels of inflammatory markers, such as erythrocyte sedimentation rate (ESR) and CRP, potentially linking to an increased risk of thyroid disease." (PMID 39600704, 2024). "Furthermore, C-reactive protein is a new inflammatory marker associated with various conditions, such as C-reactive protein to lymphocyte count ratio, and has been studied and found to be elevated in patients with thyroiditis.." (PMID 39470502, 2024). "It is unclear if C-reactive protein is associated with thyroid function other than thyroiditis." (PMID 17185277, 2006). "To assess the influence of transient conditions such as thyroiditis, we performed a sensitivity analysis excluding patients with elevated CRP or ESR within 2 weeks of the initial low TSH measurement." (PMID 41196264, 2025). "Elevated levels of ESR and CRP, in addition to the other noted symptoms, were indicative of thyroiditis, and a sonogram was suggested to be done." (PMID 37489189, 2023). "Since CRP levels tend to decrease in BD patients on lithium monotherapy, lithium treatment would be expected to mask the elevated levels of CRP in thyroid disorders, if the analysis were to be based solely on the serum CRP levels." (PMID 29352395, 2018). "The aim of this study was the evaluation of serum C-reactive protein (CRP) concentration as a marker of the inflammatory state in many different thyroid diseases and its dependence on the stage and duration of disease." (PMID 24794233, 2014). "The aim of this study was to approach the evaluation of serum high-sensitive CRP (Hs-CRP) concentration as a marker of the inflammatory state in many different thyroid diseases and its dependence on the stage and duration of disease." (PMID 24794233, 2014). "Previous studies have reported marked variations in serum CRP levels with different thyroid disease entities." (PMID 21151525, 2010). "In this small series of patients, a comparison of symptoms allowed the following findings: symptoms consistent with painless thyroiditis presented earlier after COVID-19 infection than their comparator, and their levels of serum CRP and IL-6 were significantly higher." (PMID 39967901, 2024). "The impact of this situation on human health requires further research, however, one might assume that some types of thyroid disease may lead to systemic inflammatory reactions that are reflected in elevated CRP levels." (PMID 24794233, 2014). "The differential diagnosis for a patient presenting with symptoms of thyroiditis, suppressed TSH, elevated free T4, ESR, CRP, and white blood cell count after experiencing viral COVID-19 infection is consistent with COVID-induced viral hyperthyroidism." (PMID 37489189, 2023). "The tests of thyroid function, erythrocyte sedimentation rate (ESR), C-reactive protein (CRP), CD64 index, T-lymphocyte subsets, and glucose-6-phosphate dehydrogenase (G6PD) were normal." (PMID 30342532, 2018). "Although CRP is not used routinely to diagnose thyroid disease, previous studies have reported that CRP was positive in patients with subacute thyroiditis compared with those having other thyroid disorders." (PMID 35741278, 2022). "Regarding inflammatory markers, WBC count, neutrophil count, and hs-CRP were significantly higher in the thyroiditis group as compared to MS without thyroiditis." (PMID 33132691, 2020). "Erythrocyte sedimentation rate (ESR) and C-reactive protein (CRP) were within normal limit, thus the diagnosis of thyroiditis was effectively ruled out." (PMID 30101044, 2018). "CRP estimations have not been routinely used to monitor thyroid disease, although many thyroid conditions involve inflammation." (PMID 21151525, 2010).
thyroiditis (continued). "Importantly, we did not observe incident thyroiditis features, thyroid dysfunction or CRP elevation at USG2." (PMID 36949763, 2023). "The observations suggest that unlike other irAEs such as pneumonitis, CRP levels and NLR were non-contributory in diagnosing CITD, whereas T cell expansion may be associated with immunotherapy-induced thyroiditis." (PMID 36568170, 2022). "His C-reactive protein was <0.04 mg/dL, and erythrocyte sedimentation rate was 6.0 mm at 1 hour, his thyroid was not tender or swollen, and TRAb was positive, indicating that we could rule out thyroiditis." (PMID 27510038, 2016). "The diagnosis of thyroiditis was based on clinical features of thyrotoxicosis, a moderately tender goitre, a suppressed TSH in the context of elevated free T3 and T4 levels, raised CRP and negative anti-thyroid antibodies." (PMID 37584380, 2023).